TPRG1L (tumor protein p63 regulated 1 like)
Description:
Presynaptic protein involved in the synaptic transmission tuning. Regulates synaptic release probability by decreasing the calcium sensitivity of release.
Synonyms: FAM79A; MOVER; RP11-46F15.3; FLJ21811; TPRGL; SVAP30; h-Mover
Tractability: Antibody: UniProt places it where antibodies can reach, with medium confidence; the Human Protein Atlas places it where antibodies can reach. PROTAC: ubiquitination databases record sites on it; its protein half-life has been measured.
Gene: Protein-coding gene on chromosome 1 (3,624,979 to 3,630,131, forward strand). Ensembl gene ENSG00000158109.
Subcellular location: Cytoplasmic vesicle, secretory vesicle, synaptic vesicle membrane; Presynaptic active zone
Subcellular location (Human Protein Atlas): Vesicles; Plasma membrane
Gene Ontology:
Molecular function: calmodulin binding; identical protein binding
Biological process: regulation of synaptic transmission, glutamatergic
Cellular component: extracellular exosome; calyx of Held; cytoplasm; presynaptic active zone; synaptic vesicle; presynapse; synaptic vesicle membrane
Genetic constraint (gnomAD): Loss-of-function variants: 24 observed, 25.92 expected, observed/expected ratio (o/e) 0.93, 90% interval 0.67 to 1.3. The synonymous counts are far from expectation, so gnomAD's model fits this gene poorly and the ratio says little. Missense variants: 353 observed, 333.7 expected, observed/expected ratio (o/e) 1.06, 90% interval 0.97 to 1.15. Synonymous variants: 182 observed, 140.01 expected, observed/expected ratio (o/e) 1.3, 90% interval 1.15 to 1.47.
Homologues: Orthologues: chimpanzee TPRG1L (100% identical), macaque TPRG1L (99% identical), dog TPRG1L (95% identical), pig TPRG1L (92% identical), mouse Tprg1l (91% identical), guinea pig TPRG1L (90% identical), rat Tprg1l (90% identical), zebrafish tprg1l (73% identical), tropical clawed frog tprg1l (67% identical). Paralogues in human: TPRG1 (44% identical).
Diseases named in the same sentence as TPRG1L in open-access papers:
TPRG1L is named in the same sentence as 8 diseases in open-access papers, as found by Europe PMC text mining. Sharing a sentence is not in itself a finding about the gene and the disease. The quoted sentences say what the papers report.
cytomegalovirus infection (1 paper, 2022). A herpesvirus infection caused by Cytomegalovirus. "Analogously, it has been found that TPRG1L upregulated IL-6 expression via NF-κB pathway in human cytomegalovirus infection." (PMID 36401185, 2022).
diabetes mellitus (1 paper, 2022). A metabolic disorder characterized by abnormally high blood sugar levels due to diminished production of insulin or insulin resistance/desensitization. "In diabetes mellitus, TPRG1L was upregulated compared with in normal people and activated the NF-κB/IL-6 axis." (PMID 36401185, 2022).
multiple sclerosis (1 paper, 2019). A progressive autoimmune disorder affecting the central nervous system resulting in demyelination. "In vivo, expression levels of TERC and TERC target genes (TYROBP, TPRG1L and USP16) are upregulated in patients with inflammation-related diseases such as type II diabetes and multiple sclerosis." (PMID 31294790, 2019). "For diabetic patients, TPRG1L and TYROBP were upregulated, whereas TYROBP and USP16 were upregulated in multiple sclerosis patients." (PMID 31294790, 2019).
cancer (3 papers, 2013 to 2022). A tumor composed of atypical neoplastic, often pleomorphic cells that invade other tissues. "Moreover, TPRG1L was significantly upregulated in GBC tissues in comparison with para-cancer tissues and negatively correlated with tRF-3013b." (PMID 36401185, 2022). "Similarly, we revealed that TERC promotes cellular inflammatory response by upregulating the expression of immune-related genes such as LIN37, TPRG1L, TYROBP and USP16 in human normal and cancer cells." (PMID 31294790, 2019).
infection (1 paper, 2020). The state of being infected such as from the introduction of a foreign agent such as serum, vaccine, antigenic substance or organism. "Multiple cellular genes were dysregulated in mutant-infected cells late in infection, of which Tumor protein p63-regulated gene 1-like protein (TPRG1L) was identified as the most highly upregulated." (PMID 32793512, 2020). "Previous observations regarding MCP-1 downregulation during late times of infection were also observed, and identified RNA1.2 as the sole or major contributor to this effect, which is likely to be driven at least in part by its downregulation of TPRG1L." (PMID 32793512, 2020).
tumor (1 paper, 2025). "Mechanistically, TRF-3013b can inhibit tumor cell proliferation and induce cell cycle arrest by binding to AGO3, which is a target of TPRG1L (tumor protein p63 regulated 1 like)." (PMID 40083327, 2025).
TPRG1L also shares sentences with these, for which no sentence is quoted: gallbladder cancer (1 paper); type II diabetes (1).